TOP2A (DNA topoisomerase II alpha)
Diseases named in the same sentence as TOP2A in open-access papers (continued):
Sharing a sentence is not in itself a finding about the gene and the disease.
primary hyperoxaluria type 1 (1 paper, 2019). A rare disorder of glyoxylate metabolism characterized by the accumulation of oxalate due to a deficiency of the peroxisomal hepatic enzyme L-alanine: glyoxylate aminotransferase (AGT). "By literature reviewing, among the five genes, four have been well documented in HCC, including: ALDOB, IGFBP3, CYP2E1 and TOP2A, while AGXT was mostly studies in primary hyperoxaluria type 1, there are little reports of AGXT in HCC." (PMID 31771612, 2019). "Among the five genes, four (ALDOB; CYP2E1; IGFBP3; TOP2A) were well documented HCC related genes, while AGXT was mostly studies in primary hyperoxaluria type 1, but had not been reported in HCC." (PMID 31771612, 2019).
Primary Immunodeficiency (1 paper, 2025).
promyelocytic leukemia (1 paper, 2019). "Another screen used DNA topoisomerase II (TOP2A) poison etoposide to identify TOP2A gene and cyclin-dependent kinase 6 (CDK6) in promyelocytic leukemia (PML) cell line HL60." (PMID 30636933, 2019).
prostate adenocarcinoma (1 paper, 2013). "This is the first study that brings together a gene and protein assessment of TOP2A in the largest series of prostate adenocarcinoma." (PMID 23398928, 2013).
RIDDLE syndrome (1 paper, 2016). A syndrome of increased radiosensitivity, immunodeficiency, mild motor control and learning difficulties, facial dysmorphism, and short stature. "Here we report that RNF168, an E3 ligase mutated in the human RIDDLE syndrome, interacts with TOP2α and mediates its ubiquitylation." (PMID 27558965, 2016). "In the present study, we report polyubiquitylation of TOP2α by RNF168, an E3 ligase known for its role in DSB signalling and being mutated in the human RIDDLE syndrome." (PMID 27558965, 2016).
seminoma (1 paper, 2025). A radiosensitive malignant germ cell tumor found in the testis (especially undescended), and extragonadal sites (anterior mediastinum and pineal gland).
steatosis (1 paper, 2025). Increased lipid within the cytoplasm of cells. "Increased abundances of Smpd3, Dtl, Cdc6, Mki67, and Top2a were detected after 14 and 42 days of feeding WD, which was consistent with the initiation and advanced phases of steatosis in hepAGT +/+ mice." (PMID 40687776, 2025). "By integrating data from the two RNA sequencing analyses, we identified five molecules related to cell division: Smpd3, Dtl, Cdc6, Mki67, and Top2a, as key mediators in suppressing WD-induced steatosis in hepAGT −/− mice." (PMID 40687776, 2025).
synovial sarcoma (1 paper, 2021). "When analyzing the effect of TOP2A expression on the four most important histological subgroups, differences in OS were only statistically significant in synovial sarcomas (64 months vs. >120 months, p = 0.021)." (PMID 34638362, 2021).
teratoma (1 paper, 2025). A non-seminomatous germ cell tumor characterized by the presence of various tissues which correspond to the different germinal layers (endoderm, mesoderm, and ectoderm). "Similarly, the miRNA regulatory network associated with teratoma hub genes demonstrates distinct miRNA clusters targeting essential oncogenic regulators such as CDK1, HSP90AA1, HSPA4, TRIM28, and TOP2A." (PMID 40869426, 2025). "Conversely, the teratoma network was dominated by CDK1, HSP90AA1, TRIM28, and TOP2A—genes critically involved in mitotic progression, chromatin remodeling, and cellular stress response." (PMID 40869426, 2025).
testicular tumor (1 paper, 2025). "A Croatian study found an association between TOP2A expression and testicular tumor antigens MAGE-A10 and NY-ESO in TNBC." (PMID 40243780, 2025).
thyroid tumor (1 paper, 2019). A benign or malignant neoplasm affecting the thyroid gland. "Immunohistochemical analysis showed that TOP2A correlated with thyroid tumor histology and it was more frequently expressed in tumors with aggressive clinical behavior." (PMID 30774662, 2019).
uterine tumor (1 paper, 2025). "We observed that TOP2A is consistently upregulated across all uterine tumor samples, with its expression levels positively correlated with mitotic activity, suggesting a potential driver role in the formation and progression of uterine tumors." (PMID 40831931, 2025).
uveal melanoma (1 paper, 2022). A melanoma derived from melanocytes of the uveal tract. "It is worth noting that uveal melanoma patients showed a ∼2% frequency of exclusive genetic alteration (deep deletion) in TOP2A." (PMID 35873470, 2022).
cancer (452 papers, 2005 to 2026). A tumor composed of atypical neoplastic, often pleomorphic cells that invade other tissues. "TOP2A encodes a protein that activates the activity of type II DNA topoisomerase and plays a pro-cancer role in NSCLC." (PMID 40092988, 2025). "These drugs bind to the complex formed by TOP2A and the cut DNA and prevent them from rejoining, causing DNA damage and cell death in cancer cells." (PMID 41439111, 2025). "•Overexpression of TOP2A stimulates multi-variant cancer progression, significantly associated with KIRC and LIHC progression." (PMID 40390492, 2025). "The identification of CCNA2, CHK1, CHK2, E2F1, and TOP2A as core genes in HCC is consistent with previous research that has linked these genes to cancer progression." (PMID 40573296, 2025). "Shared pseudotemporally correlated genes between both integrated datasets included genes associated with proliferation (CENPF and TOP2A), cancer‐associated fibroblasts (DCN and COL1A1) and neurodevelopment (HMGB2 and NPAS3)." (PMID 39836549, 2025). "Although its overexpression is associated with poor prognosis in various cancers, the expression of TOP2A is tightly regulated by epigenetic mechanisms, particularly DNA methylation." (PMID 40746357, 2025). "Abnormal TOP2A expression is associated with various cancers, particularly in rapidly proliferating tumor cells, where its levels are often significantly elevated." (PMID 39910812, 2025). "TOP2A, an essential enzyme for DNA replication and transcription, is also implicated in cancer progression, including EC." (PMID 39910812, 2025). "TOP2A is highly expressed in proliferating cells, and its upregulation is closely associated with a broad range of cancers, including OC." (PMID 41235254, 2025). "Previous studies clearly indicated that the activation of TOP2A was associated with cell proliferation, chemotherapy resistance, and disease aggressiveness of variety of human cancers." (PMID 38957610, 2024). "Topoisomerase II α (TOP2A) is commonly regarded as an oncogene that is associated with malignant disease progression in a variety of cancers, its mechanistic functions in OC have yet to be firmly established." (PMID 38445610, 2024). "Type IIA topoisomerase (TOP2A) is significantly associated with malignant tumor development, invasion, treatment and its prognosis, and has been shown to be a therapeutic target against cancer." (PMID 37407689, 2023). "A meta-analysis showed that high TOP2A expression is associated with a worse prognosis in many types of cancer." (PMID 36982681, 2023). "The results showed that TOP2A was the gene most closely associated with EZH2 in various cancer types, including HCC." (PMID 38008711, 2023). "Pathway analysis further illustrated the relationship between 25 overlapping BM-related genes and cancer-related pathways, showing that TOP2A was closely associated with the activity of EMT and cell cycle pathway." (PMID 37980167, 2023). "Top2a protein levels have been correlated with proliferation rate and the carcinogenesis of neoplasms in multiple types of cancers, and Top2a expression is associated with poor prognoses." (PMID 36678591, 2023). "Here, we explored the potential carcinogenic function and the association with clinical outcomes of TOP2A in 33 different human cancers." (PMID 35873470, 2022). "Changes in DNA structure during the cell cycle are complex and diverse, and TOP2A alters the structure of DNA along with the potential function of many genes, thereby resulting in a range of cancer-associated functional loci." (PMID 36004205, 2022). "Genetic alterations in TOP2A were dominated by amplification and mutation types, which differs in different cancer types." (PMID 35778520, 2022). "TOP2A expression was generally positively correlated with cancer associated fibroblasts, M0 and M1 macrophages in most cancer types." (PMID 35778520, 2022).
cancer (continued). "TOP2A, as a DNA topology changer in various DNA associated processes (i.e., replication, chromosome segregation, recombination), is a well-known anti-cancer drug target." (PMID 36304266, 2022). "TOP2A expression was generally positively correlated with cancer associated fibroblasts, M0 and M1 macrophages, and immune checkpoints." (PMID 35778520, 2022). "Sequentially, we explored the potential association between genetic alteration of TOP2A and clinical prognosis in different cancer types." (PMID 35778520, 2022). "FGFR1 loss and TOP2A loss are promising new biomarkers that independently identify a subgroup of triple negative poor prognosis PABC patients that require personalized cancer treatment." (PMID 35792986, 2022). "Upregulated TOP2A has been reported in different cancers and is identified to be associated with poor prognosis." (PMID 35873470, 2022). "We chose the cancer types in which TOP2A was associated with poor OS by Log-rank test and the Kaplan–Meier survival curve simultaneously." (PMID 35778520, 2022). "Topoisomerase II (TOP2A) is a gene encoding enzyme involved in DNA replication associated with anthracycline resistance in various cancers." (PMID 36408344, 2022). "In the SNV percentage analysis, we found that the number of samples in which the topoisomerase family genes occurred deleterious mutation was greater in UCEC and SKCM, such as the TOP2A with the highest mutation frequency among all cancer types." (PMID 36288358, 2022). "TOP2A silencing reduces the phosphorylation of Smad2 and Smad3 and impairs the malignant characteristics of cancer cells, which is implicated in the carcinogenesis of high-grade serous OC." (PMID 34787052, 2021). "As is the case for Top2α, compounds that reversibly stabilize Top1cc are termed Top1 poisons since these result in persistent DNA double-strand breaks that cause cancer cells to undergo apoptosis." (PMID 34532656, 2021). "Although TOP2A expression predicts the aggressive phenotype of cancers, the underlying molecular mechanisms have remained unreported." (PMID 34939898, 2021). "Among all forms of topoisomerase, TOP2A is mainly involved in cell proliferation and overexpressed in a variety of cancers, and its overexpression causes the poor prognosis of these malignant tumors." (PMID 34257537, 2021). "The TOP2A gene causes chromosomal instability in many different cancers, and its protein expression level is linked to advanced tumor stages and chemotherapeutic resistance via inhibition of apoptosis." (PMID 34070979, 2021). "It has been reported that aberrant expression of TOP2A is implicated in malignant transformation of cancer cells, e.g., proliferation, metastasis, and chemotherapeutic drug resistance." (PMID 32977589, 2020). "Six of these validated genes (BIRC5, MK167, MMP9, PLOD2, and TOP2A) have previously been implicated ccRCC,21, 22, 23, 24, 25, 26, 27, 28, 29, 30, 31, 32, 33, 34 while the others have been implicated in other cancers." (PMID 32986937, 2020). "Although many resistance mechanisms have been defined, acquired resistance of human cancer cell lines to TOP2α interfacial inhibitors/poisons is frequently associated with a reduction of Top2α/170 expression levels." (PMID 32566920, 2020). "Accumulating studies revealed that CCNB1, CCNB2 and TOP2A are associated with the prognosis of cancer and active carcinoma pathogenesis 38-40." (PMID 32201520, 2020). "The TOP2A enzyme has been implicated in multiple cancers due to its involvement in DNA replication, transcription, and chromatin remodeling." (PMID 32977589, 2020). "We found that TOP2A was overexpressed in BLCA, and higher TOP2A expression was associated with poorer cancer-specific, progression-free and recurrence-free survival." (PMID 31216997, 2019).
cancer (continued). "Univariable COX regression analysis revealed high TOP2A expression was significantly associated with poorer cancer-specific, progression-free and recurrence-free survival, but not independently of clinical characteristics in the multivariable models." (PMID 31216997, 2019). "Meanwhile, clinical significance analysis showed that TOP2A expression was associated with cancer subtype, patients gender and smoking." (PMID 31528121, 2019). "TOP2A acts as a target for many anti-cancer agents, with many mutations in it being associated with drug resistance." (PMID 31595147, 2019). "Further studies should be carried out to explore the mechanisms underlying the role of TOP2A during cancer pathogenesis." (PMID 31886163, 2019). "Whereas reduction in Topo IIα levels led to amsacrine resistance in murine P388 leukemia cells several mutations in TOP2A were also associated with the development of drug resistance in human cancers." (PMID 29966298, 2018). "Other cancer-associated genes such as Top2a, Ptn, Ptk7, Tnc and Mmp14 were highly expressed in DAKO mice." (PMID 28459858, 2017). "Here, we report that RNF168 interacts with TOP2α to mediate its polyubiquitylation, and we further show that RNF168 deficiency confers resistance to ICRF-193, a TOP2 catalytic inhibitor, and etoposide (VP-16), a TOP2 poison and cytotoxic anti-cancer drug." (PMID 27558965, 2016). "In vivo, during cancer progression, cells have evolved mechanisms to circumvent programmed cell death associated with high level of TOP2A." (PMID 26560244, 2015). "For example, the aberrant regulation of ERCC1, TYMS, TUBB3, RRM1 and TOP2A is associated with the abnormal proliferation of cancer cells, according to the hallmarks of cancer that were proposed previously." (PMID 24926347, 2014). "The topoisomerase IIα (TOP2A) gene encodes an enzyme that is involved in DNA replication, and is associated with the sensitivity to anthracycline therapy in various carcinomas." (PMID 24926347, 2014). "Consistent with its role in cell proliferation, genetic aberrations in TOP2A are linked to numerous human cancers." (PMID 22111588, 2011). "Recurrent gain of 7p15-p21 and 17q22-qter has been associated with poor overall survival, and increased copy number and expression of topoisomerase II-α (TOP2A) in 17q21.2 have been associated with poor cancer-specific survival and presence of metastasis." (PMID 18522746, 2008). "The expression level of TOP2A was also determined, since increased expression of TOP2A has been associated with poor cancer-specific survival in MPNSTs." (PMID 18522746, 2008). "Recent studies have shown that co-amplification of HER2 and TOP2A is associated with sensitivity to anthracycline therapy in several types of cancer." (PMID 19061514, 2008). "Many genes with differential expression have been associated with GC and other cancers in other reports, such as topoisomerase (top2A) and cdc25B." (PMID 19412438, 2007). "The TOP2A gene, which was associated with the high-risk tumors, was recently identified as one of the genes of a general cancer metasignature." (PMID 16280042, 2005). "Notably, cross-cancer studies have provided clues regarding the association between TOP2A and drug resistance pathways." (PMID 41235254, 2025). "Overexpression of TOP2A is associated not only with tumorigenesis and cancer progression in various types of cancer, such as breast, hepatocellular, colorectal, lung, and ovarian, but also with increased proliferation, angiogenesis, metastasis, and drug resistance." (PMID 40564876, 2025). "The inhibition of TOP2A has been associated with reduced tumorigenesis of various cancers." (PMID 38957610, 2024). "Cancer cells with ID17 were found to carry a mutation in Top2α Lys743Asn (Top2α-K743N)." (PMID 39408578, 2024). "TOP2A is both a gene in this six-gene signature risk model and a target for anti-cancer drugs." (PMID 39063036, 2024).